ABCC8 (ATP binding cassette subfamily C member 8)
Diseases named in the same sentence as ABCC8 in open-access papers (continued):
Sharing a sentence is not in itself a finding about the gene and the disease.
neonatal diabetes mellitus (31 papers, 2010 to 2026). Neonatal diabetes mellitus presents as hyperglycemia, failure to thrive and, in some cases, dehydration and ketoacidosis which may be severe with coma, in a child within the first months of life. "As for the Kir6.2 subunit, gain-of-function (GOF) mutations (KCNJ11/ABCC8) in the Kir6.2 subunits of pancreatic KATP channels have been identified as the most common cause of human neonatal diabetes mellitus, nDM." (PMID 39065708, 2024). "According to recent reports, diseases caused by ABCC8 mutations fall into the following categories: HH, permanent neonatal diabetes mellitus, transient neonatal diabetes mellitus, and pulmonary arterial hypertension." (PMID 38212772, 2024). "Other ABCC8 gene mutations that have relatively mild effects on KATP channel function compared to those seen in permanent neonatal diabetes mellitus cause transient neonatal diabetes mellitus." (PMID 38212772, 2024). "At least 14 ABCC8 mutations have been identified in patients with permanent neonatal diabetes mellitus." (PMID 38212772, 2024). "The most frequent genetic causes of neonatal diabetes mellitus with abnormal β cell function are abnormalities of the 6q24 locus and mutations of the ABCC8 or KCNJ11 genes coding for the potassium channel in the pancreatic β cell." (PMID 33102403, 2020). "Mutations in genes encoding KATP channel proteins—KCNJ11 (encoding Kir6.2) and ABCC8 (encoding SUR1)—lead to neonatal diabetes mellitus." (PMID 24324494, 2013). "The ABCC8 gene is known to harbor ~ 14 activating variants linked to neonatal diabetes mellitus (NDM) and over 300 inactivating mutations associated with congenital hyperinsulinism via their impact on the SUR1-regulated KATP channel." (PMID 40981175, 2025). "The gene of adenosine triphosphate (ATP)-binding cassette subfamily C member 8 (ABCC8) is reported to be associated with the MODY12 subtype, permanent or transient neonatal diabetes mellitus, and an opposite phenotype: hyperinsulinemic hypoglycemia." (PMID 36836406, 2023). "Six patients of Group 2 carried a pathogenic or likely pathogenic variant in KCNJ11 (3 variants), ABCC8 (1 variant) and PDX1 (biallelic variants); a patient with transient neonatal diabetes mellitus had 6q24 methylation defects (Online resource 1, left panel)." (PMID 36178555, 2023). "Gain-of-function mutations in the genes that encode either subunit, ABCC8 (SUR1) or KCNJ11 (Kir6.2), lead to channel hyperactivity, which attenuates the insulin response to hyperglycemia and causes neonatal diabetes mellitus (ND)." (PMID 25926814, 2015). "Nucleotide variations in genes encoding KATP channel proteins, such as potassium channel inwardly rectifying subfamily J member 11 (KCNJ11) and ATP-binding cassette, subfamily C, member 8 (ABCC8), are associated with the onset of neonatal diabetes mellitus." (PMID 26161088, 2015). "Similarly, variants in KCNJ11, ABCC8 and INS accounted for 50% of neonatal diabetes mellitus (NDM) cases and were sequenced by Sanger first in some studies." (PMID 37794142, 2023). "Research has demonstrated that the most common mutation sites associated with Neonatal Diabetes Mellitus (NDM) are located within the KCNJ11 and ABCC8 genes, which encode the Kir6.2 and SUR1 subunits of the KATP channel, respectively." (PMID 40650956, 2025). "For example, among the 19 diseases with ‘Ketosis’ as clinical sign, two of them were classified as oligogenic: maple syrup urine disease with 3 genes (BCKDHA, BCKDHB and DBT) and Permanent neonatal diabetes mellitus with 4 genes (GCK, INS, KCNJ11 and ABCC8)." (PMID 28715999, 2017). "Interestingly, SNPs in ABCC8 and KCNJ11 were reported in patients with neonatal diabetes mellitus and DCD." (PMID 38137073, 2023).
neonatal diabetes mellitus (continued). "The variants in ABCC8 gene encoding the SUR1 subunit of KATP could cause a variety of phenotypes, including neonatal diabetes mellitus (ABCC8-NDM) and ABCC8-induced nonneonatal diabetes mellitus (ABCC8-NNDM)." (PMID 34631896, 2021). "Accurate molecular diagnosis of monogenic non-autoimmune neonatal diabetes mellitus (NDM) is critical for patient care, as patients carrying a mutation in KCNJ11 or ABCC8 can be treated by oral sulfonylurea drugs instead of insulin therapy." (PMID 21049026, 2010).
hyperinsulinemic hypoglycemia (20 papers, 2012 to 2025). An inherited autosomal recessive syndrome characterized by the disorganized formation of new islets in the pancreas and congenital hyperinsulinism. "This study used targeted exon sequencing to investigate genetic variants of ABCC8 and the associated phenotypic features in Chinese patients with hyperinsulinemic hypoglycemia (HH)." (PMID 38212772, 2024). "Paternally inherited loss-of-function (LOF) ABCC8 mutations represent a known mechanism in autosomal-recessive hyperinsulinemic hypoglycemia." (PMID 38791571, 2024). "We present the genotype–phenotype correlation in patients with early-onset hyperinsulinemic hypoglycemia (HH) caused by different mutations in the ABCC8 gene." (PMID 38791571, 2024). "Furthermore, ABCC8 gene variants can cause hyperinsulinemic hypoglycemia due to inactivating mutations that impair the magnesium-ADP-mediated opening of the channel." (PMID 39859454, 2025). "Notably, we observed two patients with pathogenic and likely pathogenic variants in GSK and ABCC8, respectively, in which mutations lead to familial hyperinsulinemic hypoglycemia." (PMID 38318288, 2023). "In patients with hyperinsulinemic hypoglycemia, familial, 1 (HHF1; OMIM: # 256450), a paternally inherited ABCC8 nonsense variant was identified by Sanger sequencing without the identification of a second variant." (PMID 36672937, 2023). "Mutations and deletions in the protein (genecards summary for ABCC8 gene) were observed in infants with hyperinsulinemic hypoglycemia." (PMID 32728190, 2020). "ABCC8 regulated K+ channel, and ABCC8/KIR6.2 channels found in insulin-secreting pancreatic beta cells are the cause of monogenic forms of hyperinsulinemic hypoglycemia and neonatal diabetes." (PMID 31607839, 2019).
Hyperglycemia (17 papers, 2012 to 2025). An increased concentration of glucose in the blood. "ABCC8 mutations can cause phenotypes who switch from HY in infancy to hyperglycemia in adolescence and even adulthood." (PMID 34408725, 2021). "Activating KCNJ11 and ABCC8 mutations cause the KATP channels to remain inappropriately open even in the presence of hyperglycemia." (PMID 34566892, 2021). "The underlying mechanism by which loss-of-function variants of ABCC8 subsequently cause the remission of HH and future hyperglycemia is complex and required to be elucidated." (PMID 34631896, 2021). "Mild hyperglycemia and the history of the previous HY point toward ABCC8/KCNJ11 or HNF1α/4α mutations, especially in late onset cases." (PMID 32928245, 2020). "In particular, in ABCC8 gene mutations, hyperglycemia generally starts in adolescence, while in HNF1α/4α in prepubertal age." (PMID 32928245, 2020). "It is known that ABCC8 mutations can cause CH, evolving into hyperglycemia and gestational diabetes." (PMID 32928245, 2020). "Persistent hyperglycemia and patient's age raised suspicion for NDM, warranting genetic testing, which identified a heterozygous pathogenic ABCC8 missense variant." (PMID 40800106, 2025). "ADRB3-rs4994 and ABCC8-rs1799854 genes showed a significant association with BMI and waist circumference, and the KCNJ11-rs5219 gene with hyperglycemia." (PMID 35560161, 2022). "Functionally, impaired insulin release driven by ABCC8 R653Q may initiate chronic postprandial hyperglycemia, which contributes to insulin resistance through downregulation of IRS1 and the PI3K–Akt pathway." (PMID 40981175, 2025). "The ABCC8 (rs1799854) gene and the KCNJ11 gene (rs5219) showed lower p-values (<0.05) in association analysis with BMI and hyperglycemia, respectively, under dominant and co-dominant models, although not statistically significant when Bonferroni correction is considered." (PMID 35560161, 2022). "In section B, the non-specific hypoglycemic pattern with hypo/hyperglycemia fluctuation points towards the ABCC8/KCJN11 mutation: if not altered, firstly GCK and then HNF1α/4α should be tested." (PMID 32928245, 2020). "In contrast to other dedifferentiation models, which present with profound hyperglycemia, this Abcc8 null model decouples hyperglycemia from increased Ca2+ influx and elegantly demonstrates that chronically active Ca2+ signaling pathways are sufficient to promote β-cell dedifferentiation." (PMID 30630689, 2019). "Activating mutations in either the KCNJ11 or ABCC8 genes encoding the two subunits (Kir6.2 and SUR1, respectively) of the ATP-sensitive potassium (KATP) channel of the β-cell membrane, prevent insulin secretion in response to hyperglycaemia and can cause both PNDM and TNDM." (PMID 24051999, 2013).
Stroke (17 papers, 2012 to 2025). Sudden impairment of blood flow to a part of the brain due to occlusion or rupture of an artery to the brain. "Colocalization analysis for sulfonylureas with any stroke and any ischemic stroke within the drug target encoding genes (± 100 kb of KCNJ11 and ABCC8 ) were performed." (PMID 37777789, 2023). "And then colocalization analysis was performed for sulfonylureas with any stroke, and any ischemic stroke within the drug target encoding genes (± 2500 base pairs of KCNJ11 and ABCC8 )." (PMID 37777789, 2023). "Using 0.7 as a posterior probability threshold, a high probability of shared casual variants for blood glucose and stroke within the encoding genes for sulfonylureas (KCNJ11 and ABCC8) was suggested." (PMID 37777789, 2023). "Colocalization supported shared casual variants for blood glucose with any stroke and any ischemic stroke within the encoding genes for sulfonylureas targets (KCNJ11 and ABCC8) (posterior probability>0.7)." (PMID 37777789, 2023). "Studies in TBI and stroke indicate that post-injury edema can be reduced and outcomes improved by either pharmacological inhibition of Abcc8 or via KO of the Abcc8 gene." (PMID 36681815, 2023). "Furthermore, gene suppression or pharmacological inhibition of Abcc8 (SUR1 gene) ameliorates brain swelling and neuroinflammation with subsequent reduction in histological damage and improvement in neurological function in stroke and TBI." (PMID 36681815, 2023).
ischemia (15 papers, 2012 to 2025). A hypoperfusion of the BLOOD through an organ or tissue caused by a PATHOLOGIC CONSTRICTION or obstruction of its BLOOD VESSELS, or an absence of BLOOD CIRCULATION. "However, ABCB1 proved to be upregulated on focal cerebral ischemia in mice, but not in rats, whereas ABCC8 showed de novo expression on ischemia in rats." (PMID 22553972, 2012).
Cerebral ischemia (12 papers, 2012 to 2024). Restriction of arterial blood supply to the brain associated with insufficient oxygenation to support the metabolic requirements of the tissue. "Sp1 is known to initiate ABCC8 transcription across various species, and targeted inhibition or genetic downregulation of Hif has been found to mitigate brain ischemia/hypoxia by reducing SUR1 overexpression." (PMID 38396807, 2024). "Utilizing the BV2 microglial cell line, they reported induction of Abcc8/Sur1 and Kcnj11/Kir6.2 following exposure to LPS + IFNγ for 48 h, as well as enhanced immunolabeling of microglia in vivo for subunits of Sur1-Kir6.2 (KATP) in cerebral ischemia." (PMID 27246103, 2016).
ischemic stroke (12 papers, 2012 to 2025). A stroke disorder caused by obstruction of blood flow to the brain, due to thrombotic (local blood clot formation) or embolic (due to a blood clot or other material traveling from another site) event. "Our findings prove significant for clinical aspects of ABC transporters: Increased mRNA levels of ABCC8 for example play an important role in genesis of cerebral edema after ischemic stroke." (PMID 22553972, 2012).
glioma (11 papers, 2020 to 2024). A benign or malignant brain and spinal cord tumor that arises from glial cells (astrocytes, oligodendrocytes, ependymal cells). "Sulfonylureas and glinides showed low cancer risks for breast, prostate, renal, and hepatic cancers and can be proposed in gastric cancer or in glioma, where the upregulation of the ABCC8 gene has been associated with poor prognosis." (PMID 37180726, 2023). "Transcriptomic data support the safe use of these drugs under these conditions as well as in gastric cancer or glioma, where the upregulation of the ABCC8 gene has been associated with poor prognosis." (PMID 37180726, 2023). "The upregulation of the ABCC8/SUR1 subunit is associated with better prognosis in pancreatic cancers and in some brain tumors like glioma." (PMID 39200356, 2024). "Conducting an extensive search using PubMed on glioma/brain-cancer-related articles of ABCC8, ABCC9, KCNJ11, KCNJ8, AQP4, and KCNMA1 genes has yielded interesting results." (PMID 39200356, 2024). "The AQP4 aggregation state similarly and significantly caused an upregulation of the KCNJ11, ABCC8, and ABCC9 genes in U87 glioma cells." (PMID 39200356, 2024). "In glioma cells, lower expression of ABCC8 (encoding SUR1, a subunit of these channels) is associated with a poor prognosis." (PMID 37834179, 2023). "Study showed that ABCC8 (ATP Binding Cassette Subfamily C Member 8) is an independent prognostic factor for glioma, which can predict chemosensitivity, and patients with high expression of ABCC8 have longer survival time." (PMID 36185201, 2022). "Another study has shown that the expression of ABCC8 mRNA can be used as an independent prognostic index in patients with glioma and can predict the sensitivity of gliomas to temozolomide." (PMID 34522968, 2021). "In this study, we collected the expression data and clinical information with respect to ABCC8 mRNA based on 656 glioma samples from CGGA database as testing set." (PMID 32728190, 2020). "Meanwhile low ABCC8 mRNA expression can be used to predict the sensitivity of glioma to radiotherapy." (PMID 32728190, 2020). "Our study found that in low ABCC8 mRNA expression glioma patients, radiotherapy was independent predictors of long OS." (PMID 32728190, 2020). "Here the expression of ABCC8 mRNA, clinical characteristics, and survival information based on 1893 glioma samples from four independent databases were analyzed." (PMID 32728190, 2020). "Our study preliminarily confirmed the expression of ABCC8 mRNA in glioma and its clinical significance." (PMID 32728190, 2020). "The expression patterns of ABCC8 in different types of gliomas were compared and the overall survival (OS) rate of glioma patients was evaluated according to the expression level of ABCC8 mRNA, and the prognostic value of this marker in gliomas was tested." (PMID 32728190, 2020). "Glioma patients with elevated expression of ABCC8 mRNA were found to have a longer survival." (PMID 35053843, 2022). "So ABCC8 mRNA expression could be an independent prognostic indicator for glioma patients and could predict the sensitivity of glioma to temozolomide." (PMID 32728190, 2020). "ABCC8 mRNA expression can be used as an independent prognostic indicator for glioma patients." (PMID 32728190, 2020). "The overall survival rate of gliomas was evaluated according to the expression level of ABCC8 mRNA." (PMID 32728190, 2020). "ABCC8 mRNA expression was a new independent prognostic index for glioma." (PMID 32728190, 2020). "However the expression and clinical significance of ABCC8 mRNA in gliomas are still unclear." (PMID 32728190, 2020). "This sugested that low ABCC8 mRNA expression could predict radiosensitivity of glioma." (PMID 32728190, 2020). "This sugested that high ABCC8 mRNA expression could predict chemosensitivity of glioma." (PMID 32728190, 2020). "However, ABCC8 was only confirmed to be an independent prognostic factor of glioma and has not been detected in any studied cell lines of PAAD." (PMID 35340619, 2022).
glioma (continued). "Subgroup analysis revealed that the high expression of ABCC8 mRNA was correlated with good OS in astrocytoma (p = 0.000), low WHO grade (p = 0.022), high WHO grade (p = 0.000), IDH mutant (p = 0.000), IDH wildtype (p = 0.007), 1p/19q codel (p = 0.000), 1p/19q non codel glioma patients (p = 0.000)." (PMID 32728190, 2020). "In the present work, we showed that the AQP4 aggregation into the pathogenic AQP4-tetramer and AQP4-OAPs differently affected the expression profile of KCNMA1, KCNJ11, ABCC8, and ABCC9 genes but not of the KCNJ8 gene in the U87 glioma cell, evaluated by the RTPCR gene expression." (PMID 39200356, 2024).
cerebral edema (10 papers, 2015 to 2024). "Additionally, studies have shown an association between intracranial pressure or cerebral edema after brain injury and several genetic SNP loci in these genes (ABCC8 and TRPM4)." (PMID 35474489, 2022). "For rs7105832 and rs3819521 in ABCC8 that were also associated with subgroups of SIDS in the present study, several studies demonstrated a relation to cerebral edema or increased intracranial pressure." (PMID 35474489, 2022). "Targeted investigations into the impact of ABCC8 and TRPM4 genetic variation on cerebral edema, intracranial hypertension, and outcome after TBI have been performed in 385–485 patients with severe TBI from a single-center." (PMID 31936452, 2020).
congenital hyperinsulinism (10 papers, 2013 to 2026). "Recessive LOF ABCC8 mutations are detected in patients with FHI/congenital hyperinsulinism, in which heterozygous individuals are healthy carriers." (PMID 38791571, 2024). "We describe the cases of two sisters who presented with hyperinsulinaemic hypoglycaemia aged 47 and 57 years old, who were subsequently diagnosed with compound heterozygous likely pathogenic variants in the ABCC8 gene, a known cause of monogenic congenital hyperinsulinism." (PMID 39153498, 2024). "Congenital hyperinsulinism (CHI) is a heterogeneous disease most frequently caused by KATP-channel (ABCC8 and KCNJ11) mutations, with neonatal or later onset, variable severity, and with focal or diffuse pancreatic involvement as the two major histological types." (PMID 28740482, 2017). "While gain-of-function mutations in ABCC8 and KCNJ11 cause neonatal diabetes, loss-of-function (LoF) mutations typically cause congenital hyperinsulinism." (PMID 41614934, 2026). "Mutations in ABCC8 (SUR1) or KCNJ11 (Kir6.2) can result in gain or loss of channel activity and cause neonatal diabetes (ND) or congenital hyperinsulinism (CHI), respectively." (PMID 25926814, 2015).